ENSG00000252296
Gene: Small nucleolar RNA gene on chromosome X (100,100,084 to 100,100,172, forward strand). Ensembl gene ENSG00000252296.
Homologues: Paralogues in human: SNORA25 (81% identical), SNORA25B (72% identical).